BTLA (B and T lymphocyte associated)
Diseases named in the same sentence as BTLA in open-access papers (continued):
Sharing a sentence is not in itself a finding about the gene and the disease.
tumor (continued). "BTLA and HAVCR2 mediate the inhibition of human tumor specific CD8 + T cells, and CD244 mediates the dysfunction of natural killer cells." (PMID 34512623, 2021). "Recently, a new co-inhibitory pair was identified as a checkpoint of the anti-tumor immune response: HVEM (herpes virus entry mediator, TNFRSF14) and BTLA (B and T lymphocyte attenuator)." (PMID 34208480, 2021). "Immune checkpoint molecules, such as CTLA4, NRP1, TNFSF15, CD44, and BTLA, are present in the TME or on the surface of tumor cells, and they negatively regulate T cell activation." (PMID 34926701, 2021). "Thus, HVEM/BTLA may represent a novel immune checkpoint during an anti-tumor immune response." (PMID 34208480, 2021). "To verify our guess, we investigated tumor-related immune checkpoints, including CD273, CD274, CTLA-4, and the ones that were newly emerging, LAG-3, TIM-3, TIGIT, CD276, BTLA, and IDO1, between the two subgroups." (PMID 33558879, 2021). "The most frequent immune targets in the CD8+ T cells from the tumor microenvironment, in descending order, of newly diagnosed patients with GBM were A2aR > PD-1 > CD39 > TIGIT > LAG-3 > CTLA- 4 > BTLA > CD160 > CD73 > KIR > TIM3." (PMID 32721947, 2020). "B-and T-lymphocyte attenuator (BTLA) is a lymphoid-specific cell surface receptor which is present on T-cells and interacts with herpes virus entry mediator (HVEM), which is present on tumor cells." (PMID 31963646, 2020). "Several targets, such as TIGIT and BTLA, have a similar frequency of expression on CD8+ T cells in healthy donors, peripheral blood from patients with GBM, and tumor-infiltrating lymphocytes (TILs)." (PMID 32721947, 2020). "These cells however overexpressed immune checkpoint inhibitory molecules, such as PD1, BTLA, TNFSF14 (LIGHT), and TIGIT, which are the sign of immune exhaustion or inhibition of tumor infiltrating lymphocytes." (PMID 30965637, 2019). "All mice daily treated with paclitaxel and anti-BTLA Ab 20 μg/mouse and 60% of animals daily treated with paclitaxel and anti-CD19 Ab were still alive 100 days after tumor challenge." (PMID 31753019, 2019). "Since anti-BTLA Ab, LY294002, and BP-1-102 had the ability to down-regulate the percentages of BTLA+CD19hi B lymphocytes in vitro, the in vivo anti-tumor effects of these molecules were further investigated." (PMID 31753019, 2019). "When considering a potential inhibitory effect of BTLA on NKT cell activation, the question remains which cell in the tumor microenvironment expresses its ligand HVEM." (PMID 29518903, 2018). "BTLA/HVEM (B and T lymphocyte attenuator/herpes virus entry mediator) pathways play a critical role in T cell suppression in tumor." (PMID 30116751, 2018). "Beyond the PD-1/PD-L1 pathway, emerging evidences show that the BTLA/HVEM pathway (B and T lymphocyte attenuator/herpes virus entry mediator) plays a key role in T cell inhibition in tumor microenvironment." (PMID 30116751, 2018). "Splenocytes were stained for coinhibitory receptors 2B4, BTLA, and PD-1 in LLC1 tumor-containing animals and unmanipulated controls." (PMID 29338031, 2018). "PD1, TIM3, BTLA, 2B4, LAG3 were markedly increased in both CD4+ and CD8+ T cells of B16F10 tumor-bearing mice compared to naive mice." (PMID 27447564, 2016). "Checkpoint inhibitors (anti-CTLA4, anti-PD-1/anti-PD-L1, anti-LAG-3, anti-BTLA), as well as agonists of CD40 or TLR, are also known to improve anti-tumor T cell survival." (PMID 25325015, 2014). "The expression of the coinhibitory markers 2B4, BTLA, and PD-1 are known to modify CD8+ T cell survival and effector function in models of both infection and tumor immunity." (PMID 24796533, 2014). "Since it is likely that many of those total CD8 T-cells from TILN are tumor specific, our data suggest that they frequently express inhibitory receptors such as CTLA-4, LAG-3, PD-1, TIM-3, BTLA and 2B4." (PMID 22347406, 2012).
tumor (continued). "Importantly, anti-BTLA significantly decreased tumor growth and improved OS in LLC-FXR tumor–bearing mice, while this treatment was less effective against LLC-Mock tumors." (PMID 40985894, 2025). "Blocking BTLA–HVEM interactions in preclinical settings has been shown to partially restore NK cell cytotoxicity and increase tumor clearance, suggesting that BTLA may be a key checkpoint in restraining NK cell-mediated immunity." (PMID 41471273, 2025). "While BTLA is not typically expressed by tumor cells themselves, its high expression on tumor-infiltrating immune cells—especially dysfunctional T cells and immunosuppressive subsets—suggests a central role in modulating the immune landscape within tumors." (PMID 41471273, 2025). "Compared to the control, neither the anti-BTLA nor the anti-PD-L1 mAbs mediated long-term survival in LLC tumor model." (PMID 40463377, 2025). "Experimental BTLA blockade in B cells, either via genetic deletion or monoclonal antibodies, has been reported to enhance antigen-specific antibody responses and increase the ability of B cells to prime CD4+ T cells in preclinical tumor models." (PMID 41471273, 2025). "Therapeutic strategies targeting BTLA to alleviate HVEM‐BTLA‐mediated suppression of T cell activity, such as the mAb Tifcemali125 and CAR‐T,126 are demonstrating significant potential in modulating anti‐tumour immunity." (PMID 40415479, 2025). "Additionally, tumor-specific CD8+ T lymphocytes often co-express PD-1 and BTLA, with BTLA+PD-1+ cells displaying greater dysfunction, including reduced IFN-γ production compared to BTLA−PD-1+ cells." (PMID 41300994, 2025). "New IC molecules, including VISTA, TIM-3, LAG-3, TIGIT, programmed cell death ligand 2 (PD-L2), B7H3, BTLA and GITR, have been identified as potential targets for overcoming tumour heterogeneity and resistance, offering potential for more effective cancer immunotherapy." (PMID 40994140, 2025). "The high-response group exhibited elevated expressions of BTLA, LGALS9, PDCD1LG2, TIGIT, TNFSF15, and VTCN1 compared to the low-response group, suggesting that patients with this tumor profile may benefit from ICIs therapy." (PMID 40761787, 2025). "In this study, BTLA expression was upregulated during treatment in LLC tumor burden mice that was not sensitive to PD-1/PD-L1 blockade." (PMID 40463377, 2025). "Importantly, HVEM/BTLA blockade immunotherapy reinvigorated antitumor immunity in TME, thereby leading to an enhanced tumor control and improved survival in FXRhiPD-L1lo mouse LLC tumors." (PMID 40985894, 2025). "BTLA expression has been linked to decreased OS and disease-free survival (DFS), independent of tumor size or stage." (PMID 41471273, 2025). "In addition, we evaluated the effects of the combination of anti-BTLA and anti-PD-L1 mAbs on infiltrating T lymphocytes in LLC tumor model." (PMID 40463377, 2025). "Inhibition of BTLA significantly decreased tumor growth and tended to reduce pulmonary metastasis but did not prevent the outgrowth of new tumors." (PMID 38233898, 2024). "Therefore, the authors suggest that inhibition of BTLA potentially contributes to the expansion of NKT-cell numbers, and the frequency of other T-cells with cytotoxic potential, resulting in reduced tumor growth." (PMID 38233898, 2024). "As shown, varied results have been observed in different cancers concerning BTLA mRNA expression in tumor and non-tumor tissue, as well as protein expression on tumor cells and TILs and its prognostic value." (PMID 38233898, 2024). "Nevertheless, the morphology of the cells suggests that the BTLA-expressing cells are tumor-inflaming immune cells and not epithelial tumor cells." (PMID 38928307, 2024). "The inhibitory receptors expressed on T cells, interacting with their corresponding ligands expressed on antigen-presenting cells or tumor cells, such as PD-1/PD-L1, CTLA-4/CD86, TIM-3/Galectin-9, TIGIT/CD155, and BTLA/HVEM, play important roles in regulating T cell functions." (PMID 39329729, 2024).
tumor (continued). "Therefore, the outcomes of HVEM interactions with BTLA or LIGHT within the TME are dichotomous: the BTLA-HVEM interaction promotes immune suppression and tumor progression, while the LIGHT-HVEM interaction drives immune activation and antitumor immunity." (PMID 39684559, 2024). "The BTLA-HVEM complex, the inhibitory immune checkpoint, may act as one of the tumor immune escape mechanisms." (PMID 38835768, 2024). "Whether surface BTLA and HVEM expression may act as a tumor suppressor in leukemic cells in CLL deserves further investigation." (PMID 37041226, 2023). "Nevertheless, it is anticipated that the intricate signaling network constituted by BTLA/HVEM/CD160/LIGHT involved in immune response regulation, tumor development and tumor microenvironment could limit therapeutic success." (PMID 37649037, 2023). "Therefore, according to these data, further studies are required to clarify more precisely the role played by the BTLA/HVEM axis in FL and DLBCL, either as a tumor suppressor or progression promoter by NF-κB pathway activation." (PMID 37649037, 2023). "Altogether, these data suggest that BTLA/HVEM axis might favor immune exhaustion and tumor evasion in CLL." (PMID 37041226, 2023). "Analysis of scRNA transcriptomic data demonstrated that tumor cells with higher UVRAG expression might also influence macrophages through receptor–ligand pairs, such as BTLA–TNFRSF14 and CCL15–CCR1." (PMID 37173968, 2023). "Increased BTLA expression was observed in mHAg-specific CD8+ T cells compared with memory effector CD8+ T cells in patients with acute myeloid leukemia and multiple myeloma, as well as constitutive expression of HVEM in mHAgs tumor cells." (PMID 37649037, 2023). "Finally, BTLA, Siglec-15, and CD39/CD73/adenosine pathways are new immune checkpoints that are being studied to promote the anti-tumor immune response." (PMID 36015348, 2022). "More specifically, it has been shown that the reduction of BTLA expression in tumor infiltrating lymphocytes (TILs), through targeting HVEM, might result in better tumor control in a humanized mouse model of PCa." (PMID 36291815, 2022). "Within the innate inflammatory cell tumor infiltrate, no expression of BTLA was observed on the macrophages." (PMID 33665363, 2021). "Moreover, it is generally accepted that the high expression of immune checkpoints such as CTLA4, PD-1, BTLA, CD274, and LAG3 will benefit tumor cells to escape immune surveillance, avoid immune-mediated apoptosis, and finally lead to poor prognosis." (PMID 34745259, 2021). "The trend for reduced expression of colonic as well as serum BTLA in MC, together with previous reports on a dominance of CD8+ T cells in the mucosa of these patients is in line with the findings of BTLA inhibiting human tumor specific CD8+ T cells." (PMID 34722568, 2021). "Moreover, CDCA7 was significantly correlated with tumor-related immunosuppressive molecules including PDCD1, CD274, CTLA4, BTLA and LAG3." (PMID 33648519, 2021). "Tim-3, LAG3, BTLA and CD160 were expressed by a mean of <2% of tumor-infiltrating CD8 T cells, and while CD244 (2B4) was present on higher numbers of CD8 T cells in cSCC, the frequencies of CD244+CD8 T cells did not significantly differ between cSCC, NS and blood." (PMID 33479027, 2021). "In contrast, TNFRSF14 binding in cis to BTLA inhibits trans interactions with LIGHT, LTA, or CD160, to maintain NK cells and T lymphocytes in a resting state, thus tuning lymphocyte activation to the surrounding tumor microenvironment." (PMID 34858395, 2021). "High tumor expression of TNFRSF14 and CD160, but not TNFSF14, LTA, or BTLA, was associated with improved BLCA patient prognosis, suggesting that the TNFRSF14–CD160 interaction, like KLRK1, is a prominent pathway of NK cell tumor surveillance in BLCA." (PMID 34858395, 2021).
tumor (continued). "Fresh cells tumor microenvironment analysis included phenotypic characterization of their T cell surfaces immune checkpoint markers PD-1, PD-L1, ICOS, TIM-3, LAG-3, 41-BB and BTLA." (PMID 34771650, 2021). "In addition, CD8A in CD8T cells was also strongly related to BTLA expression, confirming the theory that the BTLA-HVEM complex signaling system promotes the tumor antigen-specific CD8 + T cells’ survival." (PMID 32793631, 2020). "On the other hand, Tils in the tumour microenvironment, especially CD8+ T cells, also express a large number of other immune checkpoint molecules, such as LAG-3, TIM-3, TIGIT, VISTA, B7-H3, and BTLA." (PMID 32775040, 2020). "Furthermore, tumor cells as seen in melanoma express HVEM and inhibit T cells’ function by interaction with BTLA." (PMID 33167514, 2020). "In addition to anti-BTLA Ab, chemotherapy combined with other BTLA-related inhibitors such as LY294002 (AKT inhibitor) or BP-1-102 (STAT3 inhibitor) can generate potent anti-tumor effects compared to chemotherapy alone." (PMID 31753019, 2019). "All mice treated with paclitaxel and anti-BTLA Ab 20 μg/mouse, 80% of the paclitaxel and BP-1-102 40 μg/mouse group and 40% of the paclitaxel and LY294002 800 μg/mouse group were still alive 100 days after tumor challenge." (PMID 31753019, 2019). "A variety of inhibitory and stimulatory receptors could co-express on tumor antigen-specific CD8+ T cells (including CD160, KLRG-1, TIM-3, 2B4, BTLA, and LAG3)." (PMID 31708918, 2019). "As summarized in a recent review addressing the immune checkpoint inhibitors in Tregs, these cells constitutively express immune checkpoints like CTLA-4 but also PD-1, BTLA, LAG-3, and TIM-3, and upregulate inhibitory receptors during activation and at tumor sites." (PMID 30233564, 2018). "In conclusion, PD-1 blockade in the PyMT tumor model was largely ineffective, whereas downregulation of BTLA surface expression reduced tumor growth and pulmonary metastasis, while it did not prevent the occurrence or outgrowth of new tumors." (PMID 29518903, 2018). "Therefore, we and other studies established that the BTLA/HVEM pathway on both circulating T cells and tumor-infiltrating T cells plays a key role in tumor immunosuppression and serves as potential targets for cancer immunotherapy." (PMID 30116751, 2018). "Given that HVEM has four known ligands, with HVEM-BTLA mediating immunosuppression and HVEM-LIGHT promoting immunostimulation, we hypothesized that recombinant HVEM protein could exert anti-tumor effects by preferentially interacting with BTLA and thus interfering with the HVEM-BTLA pathway." (PMID 39979981, 2025). "While our results show that both UDCA and DHP dose-dependently reduced tumor growth in mouse LLC tumor models, we hypothesized that HVEM/BTLA blockade would be combined with FXR antagonists to provide additional therapeutic benefit in NSCLC, especially for the FXRhiPD-L1lo subgroup." (PMID 40985894, 2025). "Augmenting of BTLA/HVEM signalling may offer therapeutic benefits in autoimmune diseases, while inhibition of this pathway could potentially enhance immune responses to tumours or pathogens." (PMID 40994140, 2025). "We assessed its co-expression with TIGIT, Tim-3, LAG-3, BTLA, and NKG2A across four groups: treatment-naïve CC patients and total CC patients, and peripheral CD8+ T cells from peripheral treatment-naive PBMCs versus tumor-infiltrating CD8+ T cells from biopsies of treatment-naive tumors." (PMID 41300994, 2025). "Moreover, BTLA-HVEM signaling is bidirectional, meaning that engagement of HVEM may also activate survival or pro-growth pathways in the tumor cell, such as NF-κB signaling." (PMID 41471273, 2025). "Similarly, increased BTLA and its ligand HVEM correlate with tumor progression and poor prognosis." (PMID 41300994, 2025).
tumor (continued). "Interestingly, high-dose HVEM-Fc did not exhibit anti-tumor activity, suggesting that simultaneous engagement of both BTLA and LIGHT at high doses may diminish or even reverse the anti-tumor effect." (PMID 39979981, 2025). "Additionally, in contrast to PD-1 and TIM-3, BTLA expression did not increase upon stimulation with tumor antigens on any NY-ESO-1-specific CD8 + subpopulation." (PMID 38233898, 2024). "The development of biologics targeting HVEM/BTLA/CD160/LIGHT is still in its infancy and will require a deeper understanding on how this pathway works during the process of T cell activation and differentiation and in the interplay tumor, tumor microenvironment, and the anti-tumor immune response." (PMID 37033927, 2023). "As a consequence, trans HVEM-BTLA interaction among adjacent tumor cells could lead to BTLA-mediated transduction of negative signals to partially hinder tumor development, leading to a kind of contact inhibition and preventing tumor proliferation." (PMID 37649037, 2023). "Another study reported that soluble PD-1, PD-L1, BTLA, BTN3A1, and pan-BTN3As levels in plasma could predict survival in 59 PDAC patients, suggesting that these soluble immune checkpoint (ICK)-related proteins could be involved in anti-tumor immunity in PDAC." (PMID 37256126, 2023). "The potential function and mechanism of BTLA on tumor cells have not been elucidated." (PMID 36552785, 2022). "Gene set enrichment analysis of exhausted CD4+ T cells from plaque and tumor MF demonstrated the significant upregulation of the PD-1 ligation pathway, which is in agreement with prior analyses investigating the MF TME, further supporting BTLA to be a surrogate marker of exhaustion." (PMID 34885092, 2021). "Additionally, tumor cells express several inhibitory molecules such as T-cell immunoglobulin and ITIM (TIGIT), T-cell immunoglobulin and mucin-domain containing-3 (TIM-3), B- and T-lymphocyte attenuator (BTLA), or CD16060." (PMID 34702924, 2021). "The visualization of exhausted BTLA+ CD4+ T cells in plaques consistently revealed their presence within the vicinity of malignant, NK, CD8+, and effector CD4+ T cells, and their densities each significantly increased in the transition from plaque MF to tumor MF." (PMID 34885092, 2021). "According to the previous research, combining PD-1 antibodies and BTLA antibodies might be of treatment effect in conditions in which tumor masses are non-homogeneous in terms of PD-1 and BTLA ligand expression." (PMID 32793631, 2020). "The clinical trial in which the registration number was NCT00854399 revealed that BTLA detected in epithelial ovarian carcinoma (EOC) tissues can predict poor outcomes of patients, and chemotherapy combined with BTLA inhibitor can enhance immune activation and produces effective anti-tumor effects." (PMID 32793631, 2020). "However, when looking at the expression level, we observed relatively high expression of LAG3 and HAVCR2 in both primary and recurrent tumor and a trend of greater expression for TIGIT, CTLA4, BTLA, and PDCD1 in recurrent tumor tissue, compared to primary tumor tissue (NS)." (PMID 33352957, 2020). "In addition to PD-1/PD-L1 and CTLA-4 antibodies which are already established in tumor immunotherapy, immune checkpoints such as LAG-3 or BTLA are emerging, which may have the potential to enhance T-cell responses alone or in combination with PD-1 blockers." (PMID 31332464, 2019). "By multivariate analysis, ≥1 cm postoperative residual tumor [≥1 cm versus < 1 cm, HR: 2.7 (95% CI 1.6–4.7), p < 0.001] and detectable BTLA expression in cancerous tissue [detectable versus non-detectable, HR: 1.8 (95% CI 1.04–3.0), p = 0.035] were independent prognostic factors for poor OS." (PMID 31753019, 2019). "None of the mice treated with paclitaxel or anti-BTLA alone could survive 70 days after tumor challenge." (PMID 31753019, 2019).